PJA1 (praja ring finger ubiquitin ligase 1)
Description:
Has E2-dependent E3 ubiquitin-protein ligase activity. Ubiquitinates MAGED1 antigen leading to its subsequent degradation by proteasome (By similarity). May be involved in protein sorting.
Synonyms: Praja1; RNF70; FLJ11830
Tractability: PROTAC: UniProt records ubiquitination sites on it; ubiquitination databases record sites on it.
Gene: Protein-coding gene on chromosome X (69,160,721 to 69,165,521, reverse strand). Ensembl gene ENSG00000181191.
Subcellular location (Human Protein Atlas): Nucleoli; Nucleoplasm
Pathways (Reactome):
Immune System: Antigen processing: Ubiquitination & Proteasome degradation
Gene Ontology:
Molecular function: protein binding; ubiquitin protein ligase activity
Cellular component: cytoplasm
Homologues: Orthologues: macaque PJA1 (97% identical), pig PJA1 (87% identical), dog PJA1 (86% identical), rat Pja1 (78% identical), mouse Pja1 (77% identical), rabbit PJA1 (58% identical), tropical clawed frog pja2 (37% identical), zebrafish pja2 (31% identical). Paralogues in human: PJA2 (48% identical).
Diseases named in the same sentence as PJA1 in open-access papers:
PJA1 is named in the same sentence as 44 diseases in open-access papers, as found by Europe PMC text mining. Sharing a sentence is not in itself a finding about the gene and the disease. The quoted sentences say what the papers report.
breast carcinoma (6 papers, 2017 to 2025). "The small molecule inhibitor RTA402 can bind PJA1 protein to inhibit its expression and, in turn, inhibit cell growth in various cancers, such as leukaemia, multiple myeloma, lymphoma, breast cancer, pancreatic cancer and colon cancer." (PMID 38906860, 2024).
glioblastoma (5 papers, 2017 to 2024). The most malignant astrocytic tumor (WHO grade IV). "In glioblastoma, CIC inactivation occurs as a result of ERK phosphorylation and subsequent degradation through interaction with the E3-ligase PJA1 or promotes nuclear export by the kinase c-Src." (PMID 33115448, 2020). "Here, the authors show that ERK activation mediates CIC regulation via ubiquitination and degradation by PJA1 and a degradation resistant form of CIC enhances efficacy of ERK inhibition in glioblastoma." (PMID 30737375, 2019). "Although the expression of PJA1 is increased in some cancers, including glioblastoma and some gastrointestinal tract cancers, detailed studies of PJA1 in HCC development and progression have not been conducted." (PMID 33457451, 2020).
glioma (3 papers, 2017 to 2021). A benign or malignant brain and spinal cord tumor that arises from glial cells (astrocytes, oligodendrocytes, ependymal cells). "Further kinases analysis revealed the association of PJA1 with cyclin-dependent kinase 1 (Cdk1, cdc2) activation, indicating a functional pathway in cell cycle, apoptosis as well as neural malignancies such as gliomas." (PMID 28966725, 2017). "Overall, mean PJA1 expression levels were highest in glioma samples compared to all other TCGA tumor types for which data are available, suggestive of its biological relevance in this tumor type." (PMID 30737375, 2019). "Our integrated genomic analyses of LGG and GBM indicate a potential new role for PJA1 in gliomas, potentially through its preciously demonstrated ubiquitination of the Smad3-likely reflecting the TGF-β tumor suppressor role in this cancer." (PMID 28966725, 2017). "In glioma TCGA data (GBM and Lower Grade Glioma), GSEA showed that PJA1-overexpressing GBMs were enriched for oncogenic Ras signaling pathways, including the finding that high PJA1 expression correlated with high ETV1 expression." (PMID 30737375, 2019). "In a TCGA study with merged cohort of Low Grade Glioma (LGG) and GBM, PJA1, PJA2 Smad3 and altered in 9%, 4% and 14% of samples, respectively." (PMID 28966725, 2017). "However, in IDH-mutant 1p/19q co-deleted low-grade gliomas (LGG) mean PJA1 expression is not statistically different between the CIC mutant versus CIC wild-type group, which is likely due to genetic loss of CIC and lack of hyperactive Ras/ERK signaling in these tumors." (PMID 30737375, 2019).
pancreatic cancer (3 papers, 2017 to 2025). "IHC staining revealed that PJA1 and GLO1 were predominantly expressed in the ductal cells of the pancreatic tumor." (PMID 40908564, 2025).
Alzheimer disease (2 papers, 2023 to 2025). A progressive, neurodegenerative disease characterized by loss of function and death of nerve cells in several areas of the brain leading to loss of cognitive function such as memory and language. "Moreover, PJA1 gene expression is downregulated in the amygdala in Alzheimer’s disease model mice and upregulated in the basolateral amygdala in mice during the formation of fear memory, suggesting a potential role for PJA1 in learning and memory." (PMID 37712419, 2023).
cognitive decline (2 papers, 2023 to 2025). "Although the changes in the blood cannot fully reflect those in the brain, these data at least indicate a potential association of GPR30/PJA1/Serpina3n with cognitive decline in postmenopausal women." (PMID 37712419, 2023).
craniofrontonasal syndrome (2 papers, 2017 to 2018). "Deletion of PJA1 was observed in patients with craniofrontonasal syndrome and associated with mild learning disabilities, whereas overexpression of PJA1 facilitates skeletal myogenesis and contributes to neural precursor development." (PMID 30185588, 2018). "Furthermore, a contiguous deletion of a region containing EFNB1, ‘Oligophrenin 1’ (OPHN1), PJA1 and EDA was reported in patients with craniofrontonasal syndrome." (PMID 28877219, 2017).
lung carcinoma (2 papers, 2019 to 2025). "PJA1 has been linked to the regulation of apoptosis by promoting forkhead box R2 (FOXR2) degradation in lung cancer cells, highlighting its multifaceted role in cell death through the ubiquitination and degradation of key proteins." (PMID 40908564, 2025).
Anxiety (1 paper, 2025). Intense feelings of nervousness, tension, or panic often arise in response to interpersonal stresses. "In the open field test, while total ambulatory distance was unchanged, Pja1 knockdown mice showed reduced ambulatory distance and residence time in the center zone (* p < 0.05), suggesting altered anxiety-like behavior." (PMID 40243483, 2025).
brain cancer (1 paper, 2017). A primary or metastatic malignant neoplasm affecting the brain. "Interestingly, although we observed PJA2 mutations in brain cancer, we found no mutations in PJA1, only alterations leading to raised PJA1 expression." (PMID 28966725, 2017).
Cirrhosis (1 paper, 2020). A chronic disorder of the liver in which liver tissue becomes scarred and is partially replaced by regenerative nodules and fibrotic tissue resulting in loss of liver function. "The strong expression of PJA1 even at the premalignant cirrhosis stage suggests that PJA1 might drive survival and proliferation of cancer progenitor cells with the potential to develop into HCC." (PMID 33457451, 2020).
liver cancer (1 paper, 2020). An epithelial or non-epithelial malignant neoplasm that arises from the liver. "These new findings suggest potential therapeutic avenues for targeting dysregulated PJA1-TGF-β signaling via cancer stem cells in liver cancers." (PMID 33457451, 2020). "Dysregulated PJA1-TGF-β signaling activates oncogenic genes and promotes tumorigenesis in human liver cancers." (PMID 33457451, 2020). "In addition, inhibition of PJA1 by treatment with E3 ligase inhibitors restores TGF-β tumor-suppressor function and suppresses liver cancer progression." (PMID 33457451, 2020). "Although our data strongly support a key role for TGF-β signaling in suppressing liver cancer and highlight how PJA1 E3 ligase inhibits TGF-β signaling, the precise mechanism of dysregulated PJA1-TGF-β signaling and its role in the stages of HCC development remain unclear." (PMID 33457451, 2020).
lung adenocarcinoma (1 paper, 2024). A carcinoma that arises from the lung and is characterized by the presence of malignant glandular epithelial cells. "Although PJA1 has been reported to be a prognostic indicator in lung adenocarcinoma and hepatocellular carcinoma, its clinical significance in NPC remains unknown." (PMID 38906860, 2024).
mental retardation (1 paper, 2017). "Interestingly, Praja1 (PJA1) has been shown to be linked to human chromosome Xq12, between markers DXS983 and DXS1216, which is an area linked to X-linked mental retardation (MRX)." (PMID 28966725, 2017).
nasopharyngeal carcinoma (1 paper, 2024). A carcinoma arising from the nasopharyngeal epithelium. "We find that PJA1 facilitates docetaxel resistance by inhibiting GSDME-mediated pyroptosis in nasopharyngeal carcinoma cells." (PMID 38906860, 2024). "Here, we identify PJA1 as a key E3 ubiquitin ligase involved in nasopharyngeal carcinoma chemoresistance that is highly expressed in nasopharyngeal carcinoma patients with nonresponse to docetaxel-cisplatin-5-fluorouracil induction chemotherapy." (PMID 38906860, 2024). "Moreover, pharmacological targeting of PJA1 with the small molecule inhibitor RTA402 enhances the docetaxel sensitivity of nasopharyngeal carcinoma in vitro and in vivo." (PMID 38906860, 2024). "Clinically, high PJA1 expression indicates inferior survival and poor clinical efficacy of TPF IC in nasopharyngeal carcinoma patients." (PMID 38906860, 2024).
orofacial cleft (1 paper, 2017). A disorder of facial skeleton that is characterized by cleft lip and/or cleft palate that result in feeding, speech and hearing problems caused by failures during development. "Associations with KLHL4, EFNB1/PJA1, CPXCR1, TBX22, and BCOR were particularly noteworthy because they are involved in syndromes that feature orofacial clefts." (PMID 28877219, 2017).
tumor (9 papers, 2017 to 2025). "Clinically, high PJA1 expression in tumours was associated with weak antitumour immunity." (PMID 38906860, 2024). "Moreover, PGAM5 expression was negatively associated with PJA1 expression in tumours in our mouse xenograft model." (PMID 38906860, 2024). "Compared with the control group, the PJA1-knockdown group exhibited reduced tumour growth in terms of size, volume and weight, and the reductions in these parameters were almost reversed by PGAM5 knockdown." (PMID 38906860, 2024). "Tumours with higher PJA1 expression were infiltrated with fewer CD3+ cells, CD8+ T cells and CD11c+ DCs, indicating weaker antitumour immunity in the corresponding NPC patients." (PMID 38906860, 2024). "Together these findings demonstrate the importance of PJA1 on tumor growth and CIC protein stability." (PMID 30737375, 2019). "To characterize this further in human tumor expression profiling data, we examined pathways correlated with PJA1-overexpression." (PMID 30737375, 2019). "The tumours in the PJA1-knockdown group were smaller and weighed less than those in the control group, especially after docetaxel administration, indicating that the tumours in the PJA1-knockdown group were more sensitive to docetaxel." (PMID 38906860, 2024). "PJA1 plays an important role as either an oncogene or a tumour suppressor in several cancers." (PMID 38906860, 2024). "In addition, the protein expression of PGAM5 was increased in the tumours of mice in the PJA1-knockdown group than those in the control group, as determined by immunohistochemical (IHC) staining." (PMID 38906860, 2024). "Moreover, IHC staining showed that DRP1 phosphorylation was decreased in PJA1-knockdown tumours, while PGAM5 knockdown abrogated this effect." (PMID 38906860, 2024). "Raised HMGA2 levels that occur with alterations in the TGF-β signaling pathway may reflect an altered activity of E3 ligases, such as PJA1, and potentially contribute to the tumor-promoting roles of TGF-β signaling." (PMID 32577156, 2020). "Moreover, knockdown of PJA1 impaired tumor growth in a xenograft model of subcutaneously injected HepG2 cells in nude mice." (PMID 33457451, 2020). "Additionally, we have previously demonstrated that PJA1 is involved in regulating tumor suppressors in the Transforming Growth Factor-β (TGF-β) signaling pathway." (PMID 28966725, 2017). "Flow cytometric analysis showed that PJA1 knockdown significantly increased the infiltration of CD11c+ DCs and CD8+ T cells, as well as the proportion of CD86+CD11c+ tumour-infiltrating DCs." (PMID 38906860, 2024). "Our recent work indicated that PJA1 promotes the ubiquitination of SPTBN1 and p-SMAD3, resulting in reduced activity of the tumor-suppressing TGF-β/SMAD3/SPTBN1-dependent pathway in HCC cells." (PMID 33457451, 2020). "PJA1 overexpression is detected in HCCs and is sufficient to suppress SMAD3- and SPTBN1-mediated TGF-β tumor suppressor signaling, promoting HCC proliferation." (PMID 33457451, 2020). "Consistently, treatment of tumour cells with the commonly used EZH2 inhibitor dZNep, which leads to degradation of PRC2 core components, selectively induces Pja1 expression." (PMID 28067271, 2017). "In this investigation, to explore a potential role for PRAJA in tumorigenesis, we conducted a genomic analysis of Praja1 (PJA1), Praja2 (PJA2) and Smad3 across 29 tumor types." (PMID 28966725, 2017). "Moreover, we observed an inverse relationship between PJA1 expression and GLO1 levels with patient survival, further supporting the hypothesis that PJA1‐dependent GLO1 degradation contributes to tumor suppression." (PMID 40908564, 2025). "We found that NPC patients with high PJA1 expression had high risks of death and tumour progression and that these patients could not benefit from TPF IC." (PMID 38906860, 2024). "Furthermore, PJA1 protein expression was increased while PGAM5 protein expression was decreased in NPC tumours with nonresponse to TPF IC than those with response." (PMID 38906860, 2024).
cancer (6 papers, 2017 to 2025). A tumor composed of atypical neoplastic, often pleomorphic cells that invade other tissues. "Therefore, we hypothesize that PJA1 plays a central role in chronic fibrosis/inflammation in the liver and cancer stem cell–associated HCC development." (PMID 33457451, 2020). "We further analyzed genetic alterations of PJA1 and PJA2 that include copy number (CPN) gain, amplification, shallow deletion, deep deletion and mutations in 36 different cancer types." (PMID 28966725, 2017). "To elucidate the mechanisms by which PJA1 regulates TGF-β signaling in cancer stem cell–associated liver tumorigenesis, we developed a novel mouse model using a hydrodynamic (rapid injection) delivery approach (PiggyBac Transposon System, System Biosciences, Inc.)." (PMID 33457451, 2020). "This study identifies a novel pathway in which the E3 ubiquitin ligase, praja ring finger ubiquitin ligase 1 (PJA1), mediates the proteasomal degradation of glyoxalase I (GLO1) exclusively in ferroptosis‐sensitive cancer cells." (PMID 40908564, 2025). "Collectively, these findings indicate that the proteasomal degradation of GLO1, mediated by PJA1, contributes to MGO accumulation, lipid peroxidation, and ferroptosis in cancer cells." (PMID 40908564, 2025). "Pja1 protein is one of the RING-finger E3 ligases that are instrumental in the regulation of inflammatory cascades, apoptosis, and cancer." (PMID 37092453, 2023). "Work from Ciechanover lab recently showed that PJA1 targets the main PRC2 components, including EZH2, to proteasome-mediated degradation in cancer cells." (PMID 28067271, 2017). "In this study, we reveal a novel pathway for GLO1 degradation in ferroptosis‐sensitive cancer cells, unlike in resistant cells, via the ubiquitin‐proteasome system (UPS) driven by praja ring finger ubiquitin ligase 1 (PJA1)." (PMID 40908564, 2025).
neurodegenerative disease (3 papers, 2022 to 2025). A disorder of the central nervous system characterized by gradual and progressive loss of neural tissue and neurologic function. "The PJA1-encoded ubiquitin ligase Ring-H2 is important for polyQ protein degradation and thus has protective potential against neurodegenerative diseases and NDDs." (PMID 36613684, 2022). "Indeed, mutations in PJA1 are associated with numerous X-linked NDDs, including neurodegenerative diseases and ASD." (PMID 36613684, 2022).
neurodevelopmental disorder (2 papers, 2020 to 2023). A behavioral and cognitive disorder with onset during the developmental period that involves impaired or aberrant development of intellectual, motor, or social functions. "The PJA1 gene is located in a specific region of the X-chromosome, and is related to neurodevelopmental disorders and is associated with craniofacial abnormalities and/or epilepsy." (PMID 37712419, 2023). "Accordingly, we focused PJA1, an E3 ubiquitin ligase involved in neurodevelopmental disorders, which was significantly and stably downregulated." (PMID 37712419, 2023).
infection (1 paper, 2018). The state of being infected such as from the introduction of a foreign agent such as serum, vaccine, antigenic substance or organism. "Thus, we demonstrate that PJA1 represses HBV promoter activation and gene transcription and thereby attenuates HBV replication and infection." (PMID 30185588, 2018).
PJA1 also shares sentences with these, for which no sentence is quoted: Parkinson disease (2 papers); schizophrenia (2); amyotrophic lateral sclerosis (1); cognitive disorder (1); craniosynostosis (1); depression (1); epilepsy (1); gastric cancer (1); gastrointestinal tract cancers (1); hepatocellular carcinoma (1); Huntington disease (1); learning disabilities (1); leukaemia (1); lymphoma (1); memory impairment (1); multiple myeloma (1); neuroblastoma (1); neurological disorders (1); non-small cell lung carcinoma (1); partial epilepsy (1); rhabdomyosarcoma (1); tauopathy (1); trigonocephaly (1).